NLRP3 (NLR family pyrin domain containing 3)
Diseases named in the same sentence as NLRP3 in open-access papers (continued):
Sharing a sentence is not in itself a finding about the gene and the disease.
diabetes (continued). "NLRP3 is also involved in metabolism and inflammation, such as gout, diabetes, insulin resistance, and obesity." (PMID 37868953, 2023). "Active oxygen species and free fatty acids activate the NLRP3 inflammasome in obesity and diabetes, contributing to the development of insulin resistance." (PMID 36768404, 2023). "Apart from these animal results, few studies have investigated the role of NLRP3 inflammasome in human models with diabetes." (PMID 36817440, 2023). "Pyroptosis mediated by activation of the NLRP3 inflammasome aggravated diabetic rat myocardial ischemia/reperfusion injury, whereas silencing the NLRP3 gene ameliorated diabetic cardiomyopathy in T2DM rats." (PMID 37993958, 2023). "Previous studies found significantly increased mRNA and protein expression of NLRP3 and pro-inflammatory cytokines in monocyte-derived macrophages in subjects with diabetes when compared with healthy controls." (PMID 36817440, 2023). "Like CVD, diabetes is a chronic disease in which inflammation plays a role in its pathophysiology, comorbidity with depression is common, and NLRP3 is thought to play a role." (PMID 37763063, 2023). "Long-term hyperglycemia is a major feature of diabetes, which induces the inflammatory response by activating the NLRP3 inflammasome to promote the production of interleukin (IL)-1β." (PMID 38127000, 2023). "The number of clinical studies addressing the role of the NLRP3 inflammasome in diabetes is very limited, but preclinical studies show a possible role of the NLRP3 pathway in the pathophysiology of type 2 diabetes." (PMID 37763063, 2023). "The nucleotide-binding oligomerization domain leucine-rich repeat and pyrin domain-containing protein 3 (NLRP3) inflammasome has emerged as a key mediator of pathological inflammation in diabetes." (PMID 38053839, 2023). "Therapeutic inhibition of the NLRP3/IL-1β system protected mice from air pollution-induced diabetes and thus points towards potential therapeutic strategies." (PMID 37400850, 2023). "Quercetin has the potential to ameliorate diabetes induced pulmonary dysfunction by targeting NLRP3." (PMID 36648717, 2023). "Previous studies have shown that AMPK activation can alleviate NLRP3 activation in individuals with diabetes." (PMID 37540330, 2023). "The deleterious effects of diabetes on the heart are increasingly being attributed to inflammatory signals from the NLRP3 inflammasome." (PMID 38067543, 2023). "The K-ATP channel Kir6.1 is potentially useful as a negative regulator of the NLRP3 inflammasome and insulin resistance, and it is a very promising target for the treatment of diabetes." (PMID 36378463, 2023). "In the past decade, the role of NLRP3 inflammasome in diabetes has been greatly appreciated, as the chronic low-grade inflammatory state accompanied by diabetes is at least partially consequent to the activation of NLRP3 inflammasome." (PMID 36817440, 2023). "MCC950, a potent and selective molecule inhibitor of the NLRP3 inflammasome, effectively inhibited macrophage pyroptosis and attenuated alveolar bone losses in diabetes mellitus–periodontitis." (PMID 37047282, 2023). "NLRP3 inflammasome plays an important role in the pathogenesis of diabetes and its representative complication, DR." (PMID 37507949, 2023). "The NLRP3 inflammasome activation in diabetes and its potential relationship with the pathogenesis of DR has been recently reviewed." (PMID 37372968, 2023). "The role of the NLRP3 inflammasome is pivotal in the pathophysiology and progression of diabetes mellitus (DM), encompassing both type 1 (T1D), or type 2 (T2D)." (PMID 37762961, 2023). "During the last decade, it has been well documented that dysregulation in NLRP3 inflammasome activity is involved in diabetes development." (PMID 37762140, 2023).
diabetes (continued). "Regarding NF-κB, it has also been observed to increase its expression in diabetes, converting pro-caspase-1 to mature caspase-1 and facilitating pyroptosis of type I alveolar epithelial cells through Toll-like receptors (TLRs) and NLRP3 pathways." (PMID 37964954, 2023). "Taken together, these results suggest that the NLRP3 inflammasome is correlated with liver pathology in pre-diabetes." (PMID 36817440, 2023). "Adjusting for WAT NLRP3 and IL1B mRNA and mostly for maximal LPS/ATP-induced IL-1β-secretion attenuated the association of plasma apoB with diabetes risk factors." (PMID 37914804, 2023). "In STZ-induced diabetic Wistar rats, myricetin decreases DPP-4 activity, its expression, and diabetes-induced NLRP3 inflammasome activation, increasing circulating GLP-1 and insulin levels." (PMID 37305094, 2023). "Myocardial injury is induced in a cellular model of diabetes when HG stimulation activates the NLRP3 inflammasome and promotes IL-1β secretion in H9C2 cells and neonatal rat ventricular myocytes (NRVM)." (PMID 36871006, 2023). "Beginning with statins, their impact in modulating NLRP3 inflammasome activation was initially shown in an experimental rat model of type 2 diabetes mellitus and diabetic cardiomyopathy." (PMID 37765019, 2023). "On the other hand, reduced NLRP3 expression in colonic NOD mouse tissue is associated with decreased microbiota dysbiosis, enhanced intestinal barrier function and diabetes prevention." (PMID 37081890, 2023). "Here, it has been proved that the active ingredients of botanical drugs can treat diabetes and its complications through NLRP3, and the botanical drugs and active ingredients are summarized, so we will not elaborate on this." (PMID 37251336, 2023). "The inflammasomes, especially the NLRP3 inflammasome, seem to play a crucial role in mediating inflammation among patients with diabetes and heart failure, CKD and cognitive impairment." (PMID 37242177, 2023). "In this review, we summarized the recent role and mechanism of H2S in regulating the NLRP3 inflammasome in diabetes, in order to provide a theoretical basis for future research." (PMID 35563208, 2022). "In diabetes, the activation of NF-κB stimulates the transcription of NLRP3 and activation of the NLRP3 inflammasome, resulting in the cleavage of caspase-1, which increases the production of mature IL-1β and IL-18." (PMID 34997266, 2022). "In this review, we summarized the recent research on H2S regulation of the NLRP3 inflammasome in diabetes to provide a theoretical reference for future related research." (PMID 35563208, 2022). "Meanwhile, NLRP3 inflammasome is also involved in the occurrence and development of diabetes, making clinical symptoms and treatment more complicated, which is one of the possible mechanisms of diabetic cardiomyopathy." (PMID 36157218, 2022). "The upregulation of LPS led to the expression of NLRP3 and IL-1β, thereby inducing the occurrence of diabetes." (PMID 35647057, 2022). "It has been reported that FTZ modulates NLRP3 inflammasome formation and activation and protects against diabetes-induced coronary damage." (PMID 36387353, 2022). "Chronic low-grade inflammation mediated by the NLRP3 inflammasome promotes pathogenesis of diabetes and its complications." (PMID 35002527, 2022). "The therapeutic efficacy of maltol on the symptoms of diabetes and neuroinflammation suggests that maltol regulates NLRP3 inflammasome activation." (PMID 36290645, 2022). "Multiple mechanisms related to aging and comorbidities such as obesity or diabetes can alter the complex process governing NLRP3 activation, leading to a chronic hyperinflammatory state." (PMID 35204152, 2022). "Inflammasomes also play an important role in liver lesions; for example, nod-like receptor family pyrin domain containing 3 (NLRP3), the best known inflammasome, and sirtuins affect liver function in diabetes, but a mechanistic assessment is still needed." (PMID 35365229, 2022).
diabetes (continued). "A study of neointimal hyperplasia in low-flow arteriovenous fistulas from HD patients showed a significantly higher NLRP3 protein amount compared to control vessels from a patient population matched with respect to age, diabetes and hypertension." (PMID 35204131, 2022). "Streptozotocin-induced diabetes aggravated I/R cardiac injury, increased the 4-hydroxynonenal, NLRP3, cleaved caspase levels, and the number of apoptotic cells." (PMID 36320147, 2022). "In diabetes, NLRP3 activation is triggered by oxidized LDLs, free fatty acids, cholesterol crystals, ceramides and uric acid, together with reactive oxygen species, elevated serum glucose levels that act as endogenous damage-associated molecular patterns." (PMID 35055149, 2022). "This is in line with previous reports, indicating that diabetes mellitus-induced VAs can be successfully treated by inhibiting the NLRP3 inflammasome." (PMID 35287557, 2022). "Based on the common pathophysiological mechanisms between AD and diabetes and the reported changes related to NLRP3 inflammasome, we analyzed miR-373 and miR-204 in neuron-derived serum exosomes in this study." (PMID 36422510, 2022). "Diabetes mellitus is another disease in which NLRP3 dysregulation has been suggested to play a pathological role." (PMID 35754962, 2022). "Diabetes triggered NLRP3, ASC, gasdermin-N, caspase-1, and collagen I expression in myocardial tissue, and promoted an increase in the serum TNF-α, IL-1β, IL-6, and IL-18 levels." (PMID 36320147, 2022). "Diabetes resulted in an increase in NLRP3 content in atrial tissue, a rise in the serum IL-1β and IL-18 concentrations." (PMID 36320147, 2022). "Targeted knockout or inhibition of RNA expression can reduce the activation of NLRP3 inflammation and delay the progression of diabetes." (PMID 36387904, 2022). "Targeted regulation of pyroptosis mediated by the NLRP3 inflammasome appears to play a critical role in the progression of diabetes." (PMID 36387904, 2022). "Here, we focused on the pathomechanism of NLRP3 inflammasome and the common mechanisms of AD with diabetes." (PMID 36422510, 2022). "MCC950 improved cardiac contractility, reduced cardiac hypertrophy and the fibrotic area, inhibited NLRP3 and caspase-1 expression, and suppressed inflammation in mice with MI and diabetes." (PMID 36320147, 2022). "In conclusion, with the further development of related research, H2S regulation of the NLRP3 inflammasome will become a new strategy for the treatment of diabetes." (PMID 35563208, 2022). "Patients with periodontitis and patients periodontitis and accompanied by type‐II diabetes had higher serum and salivary NLRP3 concentrations when compared to healthy individuals or patients with diabetes only." (PMID 35909305, 2022). "The NLRP3 inflammasome has been reported to be the most well-studied inflammasome, and the role of the NLRP3 inflammasome in various diseases, such as cancer, diabetes, and neurodegenerative diseases." (PMID 36232980, 2022). "There is a well-studied relationship between glucose metabolism abnormalities, diabetes and IL-1β-mediated NLRP3 activation." (PMID 35055149, 2022). "TXNIP, which is involved in the activation of the NLRP3 inflammasome, is closely related to the onset of type 2 diabetes mellitus." (PMID 36452319, 2022). "NLRP3 inflammasome activation is known to contribute to diabetes and dementia by triggering IL-1β maturation." (PMID 35958024, 2022). "NLRP3 inflammasome, IL-1β, and IL-18 can affect blood glucose control and insulin resistance, which are related to the pathogenesis of diabetes, and play an important role in diabetes-induced systemic chronic inflammation and insulin signal transduction." (PMID 36248820, 2022). "The results showed that the levels of NLRP3 in the kidneys of the diabetes group were higher than those in the normal group (P < 0.05), but the level of NLRP1 did not change significantly compared with that of the normal group (P > 0.05)." (PMID 35399795, 2022).
diabetes (continued). "Some natural substances also delayed the progression of diabetes and its complications by inhibiting the NLRP3 inflammasome-mediated pyroptosis pathway." (PMID 36387904, 2022). "Recent studies have shown that pyroptosis, especially the NLRP3 inflammasome-mediated pyroptosis, plays a vital role in the progression of diabetes and its complications." (PMID 36387904, 2022). "The NLRP3 inflammasome is attracting attention because it contributes to the pathogenesis of metabolic and degeneration diseases, such as diabetes and neurological disorders." (PMID 36290645, 2022). "Recent studies have examined the inflammatory and pre-apoptotic role of NLRP3 inflammasomes in diabetes and its complications." (PMID 35655729, 2022). "TXNIP plays a potential role in sterile inflammatory processes and innate immunity through the activation and releasing of IL-1β by the NLRP3 inflammasome in diabetes and oxidative stress." (PMID 36017183, 2022). "The expression levels of TC, LDL, FPG, PBG, HOMA-IR, GSP, liver weight/BW, and NLRP3 in the diabetes group were significantly higher after the modeling was completed (P < 0.05)." (PMID 36532503, 2022). "Given the mean of the groups, it was found that induction of diabetes significantly increased the expression of the NLRP3 gene in the diabetic neuropathy rats compared to the healthy group (P < 0.05)." (PMID 35655729, 2022). "For example, metformin, a first-line drug for diabetes treatment, inhibited the activation of NLRP3 inflammasome and cardiomyocyte pyroptosis, reducing myocardial ischemia-reperfusion injury." (PMID 36387904, 2022). "In conclusion, excessive generation of ROS and NLRP3 inflammasome activation trigger inflammation and pyroptosis in diabetes." (PMID 35355717, 2022). "Diabetes triggered NLRP3, ASC, gasdermin-N, caspase-1, and collagen I expression and increased the number of TUNEL positive cells in myocardial tissue of ob/ob mice." (PMID 36320147, 2022). "A previous study also showed that the expressions of NEK7 and NLRP3 inflammasome in vascular cells of patients with diabetes were significantly increased." (PMID 36248820, 2022). "Current studies have shown that MCC950, a potent and selective small-molecule inhibitor of NLRP3, has therapeutic effects in several renal diseases, diabetes, and its complications." (PMID 35873572, 2022). "One study demonstrated that NLRP3 activation was increased in monocyte-derived macrophages from patients with diabetes as well as in the endothelial cells of diabetic mice." (PMID 35563363, 2022). "The findings provide new insights into the NLRP3 inflammasome activation and pyroptosis in vascular endothelium, which is important for studying diabetes-related atherosclerotic coronary artery disease progression and therapy." (PMID 36425580, 2022). "Tai Chi intervention can reduce blood glucose, blood lipid, and insulin resistance levels and decrease the serum levels of inflammatory factors, including NF-κB, ROS, NLRP3, IL-1β, and IL-18 in pre-diabetes." (PMID 36248820, 2022). "Ibrutinib treatment also attenuates NF-κB and NLRP3 inflammasome activation in metabolic inflammation in an in vivo murine model of diabetes mellitus." (PMID 36521376, 2022). "In the context of diabetes, hyperglycemia would lead to mitochondrial dysfunction and oxidative stress, as well as chronic inflammation, all of which shall induce the NLRP3 inflammasome." (PMID 35204152, 2022). "It has been reported that NLRP3 is activated in different types of diabetes, while NLRP3 depletion seemed to have a protective effect against diabetes." (PMID 36405726, 2022). "Studies have shown that NLRP3 inflammasome activation plays an important role in the development of diabetes and diabetic complications." (PMID 34055976, 2021). "Here, we discuss the role of lncRNAs in regulating NLRP3 inflammasome as well as its participation in diabetes and diabetic complications, providing novel insights into developing future therapeutic approaches for diabetes." (PMID 35087834, 2021).
diabetes (continued). "The present study demonstrated that TREM2 modulates high glucose-induced microglial inflammation via the NLRP3 signaling pathway providing evidence for the study of chronic neuroinflammation and the immunometabolic response in diabetes neuroinflammation." (PMID 34356130, 2021). "More and more experimental evidence show that the activation of NLRP3 inflammasome is closely related to some immune related diseases, such as gout, multiple sclerosis, diabetes, ulcerative colitis and AD." (PMID 34381452, 2021). "Chronic hyperglycemia has long been associated with brain endothelial complications in diabetes and metabolic disorders through different signaling cascades, including the TXNIP/NLRP-3 pathway." (PMID 34681207, 2021). "Clinical and laboratory data both have shown that NLRP3 inflammasome plays a vital role in metaflammation and contributes to the progression of diabetes and several diabetic complications." (PMID 34631209, 2021). "Recently, growing evidences hint that regulating lncRNAs on NLRP3 inflammasome is critical in developing and progressing diabetes and diabetic complications." (PMID 35087834, 2021). "Previous studies found the overexpression of NLRP3, caspase-1, and IL-1 in the heart of rats with diabetes." (PMID 35145423, 2021). "Diabetes and its complications activate NLRP3 inflammasome through hyperglycemia, hypercholesterolemia, and hyperuricemia, resulting in a rise of IL-1β and IL-18 levels and inducing inflammatory response." (PMID 35087834, 2021). "In 2011, Menu and Vince recapitulated the role of abnormal activation of NLRP3 inflammasome and the overexpression of IL-1β in the development of diabetes and in its complications." (PMID 33546399, 2021). "Obviously, MALAT1 regulates diabetes-related retinal vessel function by activating ASK1/p38/NLRP3 signaling pathway." (PMID 35087834, 2021). "Simultaneously, the function of NLRP3 inflammasome provides a vital theoretical basis for using lncRNA as a therapeutic target to treat diabetes complications." (PMID 35087834, 2021). "In vitro analysis dissected the decreased activation rate of NLRP3 inflammasome in the murine ApoE−/− model and impeded atherosclerotic process in diabetes." (PMID 34443594, 2021). "Accumulating evidences indicate that NLRP3 inflammasome contributes to the development of diabetes and diabetic complications and that NLRP3 inflammation inactivation is beneficial in treating these illnesses." (PMID 35087834, 2021). "In this review, we summarized the role of NLRP3 inflammasome in diabetes and several diabetic complications, as well as 31 active compounds that exert therapeutic effect on diabetic complications via inhibiting NLRP3 inflammasome." (PMID 34631209, 2021). "Metformin can inhibit the NLRP3 inflammasome activation in apolipoprotein E (apoE) -/- mice and inhibit diabetes-accelerated AS, at least in part by activating AMPK and regulating thioredoxin-1/thioredoxin interacting protein." (PMID 34163481, 2021). "More evidence for connections between NLRP3 inflammasomes, NETosis, and promotion of chronic systemic inflammation can be found in studies of diabetes." (PMID 34639062, 2021). "Recently, accumulating evidence has shown that various active agents from herbal medicine can ameliorate diabetes and diabetic complications via inhibiting the NLRP3 inflammasome." (PMID 34631209, 2021). "In this review, the effects of ERS on NLRP3 inflammasome and its mechanism are explored in diabetes to provide ideas for the relevant basic research in the future." (PMID 33937267, 2021). "Accumulating evidence has shown the intrinsic relationship between NLRP3 inflammasome and diabetes from various aspects." (PMID 34631209, 2021). "Recent evidence shows that diabetes-mediated increases in ET-1 in hippocampal neurons induce NLRP3 activation and inflammation." (PMID 33917140, 2021).